KRAS (KRas proto-oncogene, GTPase)
Diseases named in the same sentence as KRAS in open-access papers (continued):
Sharing a sentence is not in itself a finding about the gene and the disease.
cancer (continued). "G12C only represents ~12% of KRAS mutations in human cancer according to the statistics from COSMIC database, but targeting other oncogenic KRAS mutations remains challenging." (PMID 37221195, 2023). "BRG1 has displayed a role in oncogenic KRAS-induced cancers with directionality seemingly dependent on cancer type." (PMID 36769189, 2023). "Pan-KRAS inhibitors, such as the one described here, have broad therapeutic implications and merit clinical investigation in patients with KRAS-driven cancers." (PMID 37258666, 2023). "In a recent study of cancer-associated VTE, somatic mutations of KRAS and STK11 were associated with thromboembolic events." (PMID 37370734, 2023). "Targeting the KRAS protein, which plays a crucial role in regulating cell growth, differentiation, and apoptosis, shows great potential as a strategy for fighting cancer." (PMID 37822837, 2023). "We identified that PAM50 LB BRCAs with high expression of LINC00426 are also enriched with different cancer-related processes, such as KRAS signaling up, epithelial-mesenchymal transition and PI3K-AKT-mTOR." (PMID 37260772, 2023). "Given the recent advances in clinical trials to directly target KRAS and GNAS mutations in other cancers, we propose a rationale to explore these mutations in future pre-clinical studies in PMP with a view for a future clinical trial." (PMID 36723696, 2023). "Here we shown that in KRAS mutant cancer cells treatment with this inhibitor elicits an effect similar to that of UHRF1 genetic ablation." (PMID 37407562, 2023). "KRAS−RASON interaction, therefore, represents a vulnerable target for the ‘undruggable’ KRAS oncogenic signaling in human cancers." (PMID 36241718, 2023). "KRAS-G12C allele-specific inhibitors exhibit promising efficacy in clinical trials and have the potential to alter the treatment status of RAS-mutant cancers." (PMID 37662925, 2023). "The RAS (KRAS, NRAS, HRAS)-RAF (ARAF, BRAF, RAF1)-MEK (MAP2K1/2)-ERK (MAPK1/3) pathway is altered in ~40% of all human cancers, mainly through oncogenic mutations in RAS (32%) and the downstream effector BRAF (~10%)." (PMID 37370689, 2023). "The KRAS protein controls GTPase, which in turn instructs cancer cells to proliferate and divide via the RAL protein." (PMID 37686543, 2023). "A similar pattern of results was observed in patients with KRAS G12C–positive cancer: median OS was significantly shorter in patients with mSTK11-mKEAP1 vs STK11 WT-KEAP1 WT (6.4 vs 15.0 months; aHR, 1.93; 95% CI, 1.35–2.75; p < 0.001)." (PMID 37069542, 2023). "Molecular characterization of CRC tumors has resulted in the identification of genetic alterations in cancer driver genes, such as KRAS, NRAS, BRAF, and ERBB2, which are now used to guide first‐line therapies." (PMID 37039257, 2023). "Within this ever-growing field, we look forward to the new technologies and approaches that researchers will utilize to help combat KRAS-mutant driven cancers in the future." (PMID 37108538, 2023). "KRAS-driven cancer cells scavenge vital proteins that contain glutamine from the extracellular space and utilize them to fuel the TCA cycle." (PMID 37110218, 2023). "Accordingly, ISG20 upregulation was associated with coagulation, epithelial-mesenchymal transition, angiogenesis, complement, and cancer/immune-related signaling, such as KRAS, PI3K-AKT-mTOR, and IL6-JAK-STAT3." (PMID 37380984, 2023). "In this study, we optimized dPCR to demonstrate KRAS genotyping in short fragmented cfDNA extracted from the plasma samples of cancer patients." (PMID 36810451, 2023). "The dimerization of oncogenic KRAS plays an important role in the activation of MAPK signaling to promote the proliferation of cancer cells." (PMID 37110848, 2023).
cancer (continued). "The analysis of data retrieved from four cancer databases (COSMIC, cBioPortal, ICGC, and TCGA) reveals significantly higher mutation rates for KRAS than for HRAS and NRAS." (PMID 36959802, 2023). "KRAS functions as a molecular switch, leading to overactivation of signaling networks that promote cancer growth and progression." (PMID 35801342, 2023). "When expressed in cells, 12VC1 alone inhibits ERK activation and the proliferation of RAS-driven cancer cell lines containing KRAS (G12V) and (G12C)." (PMID 37592990, 2023). "The inhibitor also inactivated 18 out of the 24 most common KRAS mutants found in cancer, when the latter were individually expressed in human embryonic kidney 293 (HEK293) cells." (PMID 37258666, 2023). "The Kirsten rat sarcoma viral oncogene homolog (KRAS) gene encodes for a small GTPase and is mutated in 25% of all cancers." (PMID 37097304, 2023). "Thirty percent of cancer cases possess active mutations in the RAS gene; however, KRAS is the most common and usually obtained in the early stages of tumorigenesis." (PMID 37899758, 2023). "Constitutive-activated KRAS mutation results from a point mutation most commonly seen in codons 12 and 13 in CRC, increasing the risk of cancer development and causing cancer cells, if formed, to proliferate uncontrollably and metastasize in the body." (PMID 36788889, 2023). "BI-3406 enhances sensitivity of KRAS-dependent cancers to MEK inhibition by modulating feedback reactivation induced by MEK inhibitors." (PMID 36831298, 2023). "In CodeBreak 100, a phase I-II trial, patients with KRAS G12C mutant cancers (mainly NSCLC, but also other malignancies, most notably colorectal) received oral sotorasib, with an aim to assess its safety and efficacy." (PMID 38067288, 2023). "Genes in the RAS family (HRAS, KRAS, NRAS) represent the most frequently mutated oncogenes in human cancers, accounting for 3.4 million cancer diagnoses each year." (PMID 37655310, 2023). "Driven by the goal of targeting key cancer drivers, we identified 16 and 28 E3 ligases targeting KRAS and EGFR, respectively." (PMID 37845222, 2023). "Oncogenic drivers in cancer, such as KRAS, can be targeted by potent inhibitors and result in remarkable therapeutic benefit." (PMID 37141389, 2023). "In this Chinese PDAC cohort, KRAS mutations were mutually exclusive with P/LP alterations in BRAF, CTNNB1, ELF3, FGF19, and other cancer‐related genes." (PMID 36999792, 2023). "In a previous transcriptome analysis, the KRAS signaling pathway was upregulated in the aggressive cancer cell line MDA-MB-231 compared to that in the MCF7 cell line." (PMID 37762678, 2023). "Future studies should explore combination therapies, predictive biomarkers, and mechanisms of resistance in KRAS-mutant cancers." (PMID 37662925, 2023). "Accordingly, lactate and granulocyte-macrophage colony-stimulating factor (GM-CSF) are known to be profoundly released from cancer cells expressing oncogenic mutant KRAS." (PMID 37444617, 2023). "Here the authors investigate E3 ligases—key to PROTAC function—and identify candidate targets for cancer drivers such as KRAS and EGFR." (PMID 37845222, 2023).
cancer (continued). "When we limited the analysis to the genes of the COSMIC Cancer Gene Census Tier 1, only four genes, including ATP2B3, CACNA1D, KRAS, and PIK3CA, showed recurrent mutations only in two patients." (PMID 37920164, 2023). "Using data from DEMETER2 and Project Achilles, we have developed a model with 20 features (the K20 model) to predict the KRAS dependency of carcinomas." (PMID 37141389, 2023). "The inflammation-dysplasia-carcinoma pathway APC dysregulation and KRAS mutations are less frequent than in CRC." (PMID 38187473, 2023). "Focusing on confirmed carcinomas (n = 11) we found four genes which were mutated in more than one sample: PIK3CA, KRAS, ZZEF1 and DOCK10 were each mutated in two of the carcinomas (18% each)." (PMID 36635367, 2023). "Our prior work described an essential role for Argonaute 2 (AGO2), of the RNA-induced silencing complex, in mutant KRAS-driven cancers." (PMID 35923912, 2022). "The data set a rational framework for the future development of effective KRAS inhibitors and design of clinical trials aimed at targeting IL-1β in cancer." (PMID 35327394, 2022). "We find EGFR-mut cancers have a significantly lower mutational burden than the other subtypes and conserve 16 genes related to DNA repair compared to 1 and 3 in NEK and KRAS-mut subtypes, respectively." (PMID 36612014, 2022). "A recent clinical study evaluated 38 patients, of which 27 with NSCLC with KRAS G12C-mutant cancers were treated with adagrasib monotherapy." (PMID 36012655, 2022). "The rat sarcoma virus (RAS) family genes (HRAS, KRAS, NRAS) are the most frequently mutated proto-oncogenes in human cancer." (PMID 36338517, 2022). "Many intracellular macromolecular interfaces exist in human cancers that are highly desirable anti-cancer therapeutic targets, such as Myc:Max, KRAS:RAF and eIF4E:4G1." (PMID 35982046, 2022). "The KRAS and Cell cycle pathways were also highly enriched in early mutations, RTK/KRAS in 7 metastatic and 4 primary cancer types, and Cell cycle in 6 metastatic and 2 primary cancer types." (PMID 36497297, 2022). "In this review, we describe the interaction between KRAS and long non-coding RNAs (lncRNAs), microRNAs (miRNAs) and circular RNAs (circRNAs), particularly in the context of cancer." (PMID 35139853, 2022). "To investigate the relevance of our findings to KRAS-mutant human cancers, we analyzed the average expression of KRAS, CCL2, and IL1B genes in public data (GSE43458) from the BATTLE trial." (PMID 35327394, 2022). "The regulation of KRAS-RAF-MEK signaling pathway has been extensively studied in cancer and significant progress has been made in targeting the cascade." (PMID 35966590, 2022). "Our study illustrates the characterization of KRAS expression in various cancer types and highlights its potential value as a predictive biomarker, which sheds light on the further investigation of the prognostic and therapeutic potential of KRAS inflammation." (PMID 35563733, 2022). "A high dose of VC is a powerful leverage in an induction of a glucose-dependent oxidative stress in KRAS-mutant cancer cells." (PMID 36359850, 2022). "A mutant KRAS gene is a biomarker for many cancer types, as this gene has controlled cell cycle division and cancer cell growth." (PMID 35163506, 2022).
cancer (continued). "Such a combination can be used to treat KRAS mutant cancer by inducing catastrophic oxidative stress." (PMID 36619305, 2022). "In fact, KRAS is regulated by multiple non-coding RNAs, and many of the non-coding RNAs are relevant at a time in cancers." (PMID 35139853, 2022). "High basal levels of autophagy are characteristic of several cancers with mutations in RAS proteins, such as H1299 (with mutant NRAS proteins) and A549 (with mutant KRAS proteins) cells." (PMID 35740374, 2022). "Mutations of the RAS family genes, consisting of HRAS, KRAS and NRAS, are involved in over 30% of all human cancers." (PMID 34580712, 2022). "RAS genes are the most frequently mutated oncogenes in cancer and among the RAS genes, KRAS mutations are most frequently associated with tumors." (PMID 36393833, 2022). "With the rapid and promising research and development of direct KRAS inhibitors, particularly against the KRASG12C mutant, there is further hope on the horizon for treating patients with cancers containing KRAS mutations." (PMID 35045886, 2022). "In the second dataset, LUSC, PIK3CA (46.5%), EGFR (7%), PDE4DIP (6.6%), KRAS (4.4%), and RELN (4.4%) were labeled with copy number gain, while CDKN2A (27.9%), LRP1B (17.4%), PTEN (9.8%), and PTPRD (9%) appeared to be the cancer genes with copy number loss." (PMID 35330454, 2022). "Cancer hallmark pathways such as epithelial-mesenchymal transition (EMT) and KRAS signaling were positively enriched in the high-risk expression subgroup." (PMID 35422861, 2022). "Mutations to oncogenic protein KRAS are responsible for some of the deadliest cancers, and KRAS is thus a key target for new antitumour agents." (PMID 36697641, 2022). "Due to the stability of the exosomes, the exosomes carrying the therapeutic short interfering RNA targeting oncogenic KRAS-expressing cancer cells are more efficient that liposomes with the same RNA cargo." (PMID 36139610, 2022). "Previous research identified that lysosome activity is vital for KRAS-driven cancer growth, but avicin G blocks the lysosome activity by elevating lysosomal PH and inhibiting the phosphorylation of ERK signaling." (PMID 35409064, 2022). "BI-3406 attenuates the feedback reactivation induced by MEK inhibitors enhancing as a consequence the sensitivity of KRAS-dependent cancers to MEK inhibition." (PMID 36077640, 2022). "The expression of CACNA1H and ORAI1 was downregulated in KRAS-mutated cells, whereas CACNA1C was upregulated in all tested cancer cells." (PMID 35267511, 2022). "MD Anderson Cancer Center in Texas published their Arab patients’ data describing that KRAS/NRAS/BRAF prevalence were 44.4%, 4%, and 4%, respectively, compared to 48.4%, 4%, and 4%, respectively, in the matched Western population." (PMID 35619874, 2022). "Mutations in proto-oncogenes (e.g., KRAS, HRAS) and tumor-suppressor genes (e.g., APC, PTEN) are the primary drivers in various cancers." (PMID 36553455, 2022). "Amplification in epidermal growth factor receptor (EGFR) signaling is a common cause of pronounced proliferation, survival, and metastasis in cancers and is one of the prime activators of KRAS." (PMID 35664781, 2022). "KRAS is part of the RAS family of GTPases that play important roles in cell proliferation and survival, with KRAS being the most common RAS mutation in cancer constituting 85% of RAS mutations in cancer." (PMID 36230484, 2022). "These combinations have been further shown to remarkably suppress the clonogenic potential of KRAS G12C–mutant cancer cells." (PMID 35573474, 2022).
cancer (continued). "KRAS G12C inhibitors in combination with selinexor suppressed the proliferation of KRAS G12C–mutant cancer cell lines in a synergistic manner." (PMID 35573474, 2022). "RAS (KRAS, NRAS, and HRAS) is the most frequently mutated gene family in cancers with the most common oncogenic mutant of the RAS family being KRAS G12C." (PMID 36530921, 2022). "Here, we investigated the underlying molecular mechanism responsible for the synergistic effect of DX2 and KRAS on tumorigenesis and explored a route to control KRAS-driven cancers." (PMID 35546148, 2022). "Oncogenic KRAS is an important mediator in metabolic reprogramming, including glucose, glutamine, and fatty acid metabolisms, for cancer cell survival, proliferation, and invasion." (PMID 35681705, 2022). "Autophagy flux provides KRAS-driven cancer cells with glutamine and glutamate to promote TCA cycling and support nucleotide production." (PMID 35922812, 2022). "In cancer cells harboring wild-type KRAS, increased KRAS induces ROS production, which is followed by increased expression of HIF-1α and YAP1." (PMID 35954483, 2022). "Time and time again, indirect inhibition strategies have resulted in disappointing clinical trial outcomes in treating KRAS-mutant cancers." (PMID 35045886, 2022). "We therefore examined the coefficients of correlations between the KRAS level and immune infiltration in various cancer types via the TIMER database." (PMID 35563733, 2022). "Most importantly, BI-3406 also attenuates MEK-in feedback reactivation, thereby enhancing the sensitivity of KRAS-mutant cancers to MEK inhibition." (PMID 35922812, 2022). "Mutations in one of the three RAS genes (HRAS, KRAS, and NRAS) are present in nearly 20% of all human cancers." (PMID 36334633, 2022). "In KRAS-mutant cancers, trametinib (MEK inhibitor) provokes a compensatory response involving the fibroblast growth factor receptor 1 (FGFR1), resulting in signaling rebound and adaptive drug resistance." (PMID 35251972, 2022). "KRAS expression has a deleterious effect on RFS in six types of cancer, including BRCA, CESC, LUAD, PAAD, KIRP, and LUSC, and protectively affects RFS survival in KIRC." (PMID 35563733, 2022). "KRAS is a signal transducer protein that binds to GTP in the MAPK pathway, and mutations have been found in a quarter of cancers." (PMID 36330448, 2022). "Elucidation of the differential consequences of the expression of the splice variants will inform the development of therapeutics designed to block KRAS driven cancer." (PMID 36393833, 2022). "LUAD has the highest mortality of human cancers, and 30% of LUAD tumors harbor oncogenic KRAS mutations; however, the role of mitochondrial dynamics in this malignancy is poorly defined compared with other KRas-driven tumors." (PMID 36516772, 2022). "In line with this, we found that human cancer cells with BRAFV600E are susceptible to LF-W271A toxins, whereas cancer cells with oncogenic KRAS mutations are less sensitive." (PMID 35899070, 2022). "RAS is the most common oncogene in cancer, and KRAS mutations are the predominant oncogene among the three RAS subtypes (HRAS, NRAS, and KRAS), which was regarded as “untreatable” targets for a long time." (PMID 35281897, 2022). "Empowered by CRISPR- and shRNA-based functional genomics, a plethora of novel factors required for KRAS-mutant cancer cells have been identified, although the long-sought-after universal synthetic lethal targets for KRAS-driven pan-cancers are still at large." (PMID 35039048, 2022). "Customized probes were designed to capture exonic regions of 141 genes selected for the panel, which was aimed for the detection of clinically actionable genetic variations in cancer, including KRAS, NRAS, BRAF, ALK, ROS1, KIT and EGFR." (PMID 35446881, 2022).